SP1 (Sp1 transcription factor)
Diseases named in the same sentence as SP1 in open-access papers (continued):
Sharing a sentence is not in itself a finding about the gene and the disease.
tumor (continued). "We found that AFAP1-AS1 and Sp1 transcription factor (Sp1) knockdown or miR-2110 overexpression suppressed MDA–MB-231 and MDA–MB-468 cell proliferation, migration, and invasion in vitro as well as tumor growth in vivo." (PMID 34145213, 2021). "In lung cancer, STRAP led to tumor progression by downregulating tumor suppressors, E-cadherin, and the CDK inhibitor, p21Cip1, through the modulation of the transcription factor Sp1." (PMID 34206917, 2021). "Following inhibition of STAT3 signalling using 5,15-diphenyl-porphine or the anti-IL-10R neutralization antibody, we observed obvious decreases in Sp1 expression on LECs and LEC attraction of M2-polarized THP-1 macrophages and tumour cells (SiHa)." (PMID 33484377, 2021). "The results indicated a significant reduction of STAT3, SP1, and SOCS5 mRNA expression in the splenocytes of CT-26 tumor-bearing mice treated with TEXomiR compared to both the TEX and PBS groups (P < 0.01)." (PMID 33987190, 2021). "Mechanistically, the results revealed that AFAP1-AS1 competitively bound to miR-2110, affecting the expression of Sp1, and thereby regulating proliferation and migration of TNBC cells and tumor progression in vivo." (PMID 34145213, 2021). "As one crucial tumor suppressor, KLF6 has been found to bind to the promoter region of SP1 and reduce its expression in HCC21." (PMID 33431838, 2021). "Some studies have shown that Sp1, as a sequence-specific DNA binding protein, could initiate the transcription of many cellular genes (including lncRNAs) and participate in various biological processes such as cell proliferation, differentiation, and tumor formation." (PMID 34145213, 2021). "After ZLM-7 treatment, protein expression of Sp1, VEGFA and MMP-2 in tumor tissues decreased when compared to control group." (PMID 33187481, 2020). "There was a positive correlation between SP1 and HIF-1α protein expression in ESCC samples, and SP1 expression was also correlated with tumor metastasis, recurrence and poor prognosis." (PMID 31892989, 2020). "The results showed that NWXF can down-regulate the expression of Sp1, MMP2, and MMP9 in tumor tissues." (PMID 33329003, 2020). "The crosstalk between two transcription factors, Sp1 and STAT3, is essential for tumour angiogenesis and metastasis." (PMID 32144747, 2020). "Surprisingly, SP1 and JUND deregulated in precancerous and tumor livers of both sexes represent nodules with most protein–protein associations linked to hepatocarcinogenesis." (PMID 33182326, 2020). "TRIM25 further degraded SP1 therefore reduces transcription and translation of MMP2, ultimately leading to reduction of angiogenesis and tumor proliferation in GC." (PMID 32576271, 2020). "We also tested the effect of SM in tumor growth and expression of CCAT1 and miR7‐5p, and SP1 in xenograft mouse model." (PMID 31823440, 2020). "The percentage of tumor cells with BMI1 or Ki67, the marker for cell proliferation, and the mean staining intensity of SP1 expression was significantly reduced in the PTC-209-pretreated group." (PMID 32726929, 2020). "It has also been suggested that Sp1 upregulates VEGF via the AKT pathway, eventually initiating angiogenesis for the invasion of tumor cells." (PMID 32050495, 2020). "In summary, our studies reveal a novel Sp1/E2F1/miR-203/Src pathway that is responsible for the activation of MMP2 and the tumor-promotive role of XIAP in BC cell invasion." (PMID 31811115, 2019). "NF-κB, AP-1, and Sp-1 are transcription factors that regulate MMP-9 expression involved in the migration and invasion of tumor cells." (PMID 31391858, 2019). "Taken together, the additive and sequential interactions of HIF1α, EGR1 and SP1 finely mediate EPO-R expression in NSCLC under hypoxia, which affects NSCLC progression and makes it response sensitively to the tumor microenvironment." (PMID 31752873, 2019).
tumor (continued). "In summary, our study demonstrates that SP1 modulates EMT and is involved in tumor invasion and migration of PDAC cells through the regulation of LOXL2." (PMID 30976063, 2019). "It was shown that PDCD4 interacts with Sp1 and Sp3 inhibiting the u-PAR expression and tumor invasion/intravasion." (PMID 31075975, 2019). "Levels of hsa-miR-149-5p and hsa-miR-21-5p and expression levels of SP1 and STAT3 proteins in tumor tissues and adjacent normal tissues of TSCC patients were ascertained." (PMID 31270251, 2019). "As a selective Sp1 inhibitor, Mithramycin A (MIT) has been reported to have anti-tumor activities in multiple cancers." (PMID 29348684, 2018). "Methylation of Sp1-binding site prevents the transcriptional activator Sp1 from binding to ZNF132 promoter, silencing ZNF132 tumor suppressor gene." (PMID 30578410, 2018). "Our data demonstrated that SP1-induced ZFAS1 contributed to CRC progression by upregulating VEGFA via competitively binding to miR-150-5p, which acts as a tumor suppressor by targeting VEGFA in CRC." (PMID 30250022, 2018). "Sp-1 is an HBx-combinative activator and a member of the Sp/KLF family oftranscription factors, and is widely overexpressed in neoplasms, including livercarcinoma." (PMID 29742265, 2018). "It is possible that Sp1 modulates/enhances the nuclear presence of ZEB2, which can contribute to the accelerated aggressiveness of malignancy and tumor progression." (PMID 29416649, 2018). "It has been reported that histone methylation is involved with VEGF expression, and that Sp1 is involved in VEGF expression and tumor growth." (PMID 30693272, 2018). "Both in vivo and in vitro treatment of AGEs accelerate the tumor invasion and metastasis, with upregualtion of RAGE, Specificity Protein 1 (Sp1), and MMP2 protein expression, as well as enhancement of MMP2 activity." (PMID 29262634, 2017). "In the early stage of tumour development, TGF‐β up‐regulated the expression of SP1 and further promoted the transcription of NKG2DLs." (PMID 28165192, 2017). "To inhibit SP1 activity, we used EC-8042, a mithramycin (MTM) analog (mithralog) with enhanced anti-tumor activity and highly improved safety." (PMID 27105533, 2016). "Increased expression of SETDB1 promotes tumor invasiveness and sensitizes anti-tumor growth by mithramycin, a SETDB1 and Sp1 inhibitor." (PMID 26824986, 2016). "The identification of the key molecules involved in tumor hypoxia adaptation confirmed that CD147 up-regulation was mainly mediated by a combined effect of HIF-1α and specificity protein 1 (Sp1) on the activation of CD147 promoter." (PMID 27009812, 2016). "The transcription factors E2F1, NF-κB, Sp1, HIF-1, AP-1, STAT3, and STAT5 play important roles in tumor cell signal transduction." (PMID 27613831, 2016). "Of importance, the higher levels of Sp1 and Nanog in biopsies are the more unfavorable prognoses of HCC patients are found after tumor resection." (PMID 27685621, 2016). "Therefore, the impact of radiation plus starvation on SP1 expression and DNA binding activity appear important to enhance tumor metastasis, and thus the combination of radiation plus starvation might be capable of maximally enhancing the metastatic ability of U251 cells." (PMID 27058528, 2016). "The transcription factors, such as E2F1, NF-κB, Sp1, HIF-1, AP-1, STAT3, and STAT5, play important roles in tumor tube formation." (PMID 27613831, 2016). "On the other side, as we all know, Sp1 is responsible for up-regulation of housekeeping genes (VEGF, uPA, uPAR and EGFR), which participate in tumour cell angiogenesis and metastasis." (PMID 25639535, 2015).
tumor (continued). "Then, we compared the mRNA levels of several TGF-β-related EMT-regulators including SNAI1, SNAI2, HMGA2, FOSL1, SP1, ZEB1, ZEB2 (SIP1), and TWIST1 in primary tumor tissues of MDA-MB-231-xenografted mice." (PMID 26462028, 2015). "The study showed that EPAS-1 plays an indispensible role in SP-1 transcription factor-mediated FBI-1 induction, and participated in tumor cell survival and proliferation." (PMID 25192290, 2014). "Several studies have reported that Sp-1 is responsible for upregulation of housekeeping genes (VEGF, uPA, uPAR, and EGFR) which participate in tumor cell angiogenesis and metastasis." (PMID 23970932, 2013). "Our results clearly implicate that CUR prevents CRC cell metastasis via inhibition of CD24 interaction with Sp-1 and FAK in CRC tumor cells." (PMID 23970932, 2013). "Upon reaching maximal allowable size, each tumor was excised and its its total TAEC population, now referred to as SP1, was again isolated." (PMID 22623986, 2012). "The SP1, MAX, RUNX1 and STAT3 sub-networks are involved in both early and late stages of the tumor but are expressed with different gene expressions." (PMID 20025723, 2009). "PKM2 is up-regulated in tumor cells, and is under control of Ras and transcription factors HIF-1, SP1, and SP2." (PMID 19221597, 2009). "If TMZ produces enough Sp1 repressors to suppress AGT activity in T98G cells, the tumour cells would be sensitised to TMZ." (PMID 12942127, 2003). "In addition to EMT regulation, Sp1 stimulates angiogenesis by directly inducing VEGF and PDGF, thereby supporting the vascular expansion required for tumor growth and metastatic spread." (PMID 41596524, 2026). "Instead, Snail's tumor-promoting activity is largely mediated through its cooperation with EGR1/SP1 transcription factors on non-canonical TCACA promoter elements, which upregulate genes such as ZEB1, MMP9, and LEF1." (PMID 42152116, 2026). "Furthermore, butyrate can activate Tyrosine Phosphatase to dephosphorylate Sp1, which inhibits the binding of Sp1 to the VEGF promoter, and leads to reduced VEGF expression and angiogenesis, subsequently diminishing tumor metastasis." (PMID 39948481, 2025). "Together, these data suggest that the transcription factor SP1 could be a transcriptional coregulator of YAP/TEAD4, which cooperatively promote tumorigenesis and tumor progression in CRC." (PMID 39875519, 2025). "Moreover, data from the GEPIA database showed that SP1 expression was also higher in PDAC tissues compared to normal tissues, suggesting its potential involvement in tumor progression." (PMID 40832790, 2025). "Expression profiles of these transcription factors in the TCGA mRNA expression dataset for HNC showed that unlike KLF5, SP1 was significantly upregulated in tumor vs. normal patient data." (PMID 40810390, 2025). "Such alterations intersect pathways implicated in endocrine biology and resistance (ERα crosstalk, AP-1/SP1/NF-κB interfaces, PI3K–AKT/MAPK signaling), offering tumor-specific hypotheses in breast, ovarian, endometrial, and colorectal settings." (PMID 41153361, 2025). "Furthermore, tumour cells and the microenvironment increasingly engage in communication through WNT signalling as metastasis progresses, driven by SP1." (PMID 39748426, 2025). "Finally, the levels of genes involved in the tumor EMT, such as CDH2, CDH11, SMAD2, SMAD3, WNT9A, and SP-1, were significantly downregulated after the SH intervention." (PMID 41444284, 2025).
tumor (continued). "Additionally, we found that tumour cells and the microenvironment increasingly communicate via WNT signalling as metastasis begins, driven by SP1." (PMID 39748426, 2025). "Combined SP1/PFKFB4 inhibition demonstrated synergy in tumor suppression without observable toxicity in mice at effective doses." (PMID 40832790, 2025). "Moreover, our results showed that as metastasis advances, tumour cells and their microenvironment increasingly communicate through WNT signalling, a process that is driven by SP1." (PMID 39748426, 2025). "The findings indicated a significant elevation in Sp1 gene methylation within tumor tissue DNA as opposed to normal control tissue." (PMID 39228402, 2024). "AURKB, as a downstream key node of the FTO/SP1/AURKB pathway, could influence the tumor microenvironment of GC." (PMID 38956367, 2024). "In addition to promoting tumor cell proliferation, leptin signaling activation upregulates cancer cell production and secretion of soluble VEGFA via NFκB, Sp1, and HIF-1α signaling to induce angiogenic sprouting into the growing tumor mass." (PMID 39439572, 2024). "SP1, SP4, SP7, and SP8, linked to suboptimal or partial chemotherapy responses, exhibited a predominant tumor cell presence (data not displayed)." (PMID 38975339, 2024). "Noteworthy, along with Sp1, the reactivation of the oncosuppressive miR-29b was accompanied by the down-regulation of other miR-29b canonical targets, i.e., MCL-1 and CDK6, suggesting a pleiotropic anti-tumor activity of this drug in MM cells." (PMID 37759449, 2023). "We also found that the binding proficiency of the Sp transcription factor family (including SP1, SP2, SP4, and SP5) (Rows 17–20) could bind GC/GT-rich promoter elements by its zinc finger structure and play a critical role in tumor growth and metastasis." (PMID 37833332, 2023). "In contrast, the silencing of AFAP1-AS1 suppressed tumor growth (group vector + sh-AFAP1-AS1 vs. group vector), which could be reversed by overexpression of SP1 (group vector + sh-AFAP1-AS1 vs. group ov-SP1 + sh-AFAP1-AS1)." (PMID 37686205, 2023). "• Inhibits transcription in tumor cells by targeting genes like RPB1, MYC, SP1 and FOS." (PMID 36969868, 2023). "In AGE-mediated tumor invasion and metastasis may be suppressed by EGCG’s inhibition of the RAGE/ERK/Sp1/MMP2 pathway." (PMID 36677584, 2023). "It was found that UVRAG could enhance tumor migration, drug resistance, and CC motif chemokine ligand 2 (CCL2) expression to recruit macrophages by upregulating SP1 expression, resulting in poor prognosis of CRC patients." (PMID 37173968, 2023). "The present study indicated that UVRAG could turn the tumor microenvironment to immunosuppression by secreting CCL2 to recruit macrophages, which was mediated by upregulating SP1 expression." (PMID 37173968, 2023). "Herein, we ascertained the levels of some epithelial and mesenchymal markers, particularly transcription factors (ZEB-1, Twist, Snail) and tyms promoter regulator SP1 with TYMS expression in the mesothelioma cancer and non-tumor adjacent tissues by bioinformatics analysis." (PMID 37894370, 2023). "In addition, SP1, HIF-1, or MYC modulates the TME, such as the immune system and the production of oncometabolites, in such a way to facilitate tumor development (as discussed in Section 2)." (PMID 37998757, 2023). "In addition, the expression of these IRGs can be regulated by the transcription factors MYB, SP1, and SP3, which are related to tumor immunity." (PMID 35463955, 2022). "In fact, both SP1 and HIF-1α positively regulate NRP1 expression in tumor cells." (PMID 35600336, 2022). "Likewise, cooperation of HIF-1α and SP1-mediated CD147 led to increased glycolysis and tumor progression in epithelial solid tumors." (PMID 35590288, 2022). "Similar to the patterns of circ-0001875 expression in NSCLC cell lines and tissues, higher expression of SP1 was observed in the tumor samples compared with that in normal samples." (PMID 35473752, 2022).
tumor (continued). "In addition to the tumor-promoting function of TUG1, our findings further identified SP1, which was an up-regulated gene in CRC, to serve an upstream mediator of TUG1." (PMID 35508523, 2022). "Moreover, consistent with the in vitro results, decreased expression of SP1 and VEGFA protein was observed in both nude mice tumor tissues fixed with paraformaldehyde and fresh tumor tissues." (PMID 36467048, 2022). "Furthermore, blockade of Sp1 dampened MDSC differentiation and infiltration in the TME and enhanced the anti-tumor therapeutic efficacy of gemcitabine." (PMID 34976216, 2022). "The relationship between Sp1 and CD44 levels was studied in normal and tumor clinical tissues." (PMID 35034634, 2022). "Also, the tumor metastasis in lung tissues, which was suppressed by sh-KDM3A, was increased after SP1 upregulation in HOS cells." (PMID 35590288, 2022). "Besides, SP1 binds to the promoter of vascular endothelial growth factor (VEGF) to facilitate angiogenesis, forming a favorable condition for tumor growth." (PMID 34257529, 2021). "The anti-tumor activity of MTM relies on its capacity to bind GC-rich DNA regions and thus inhibit the gene expression mediated by pro-oncogenic transcription factors such as SP1." (PMID 33806182, 2021). "Importantly, we confirmed that blockade of Sp1 or CCL1 prevented TAM proximity to LVs, thereby reducing tumour lymphangiogenesis and metastatic dissemination." (PMID 33484377, 2021). "However, our recent report demonstrated SNA collaborates with EGR1 and SP1 to directly upregulate MMP9 and ZEB1 stimulated by the phorbol ester tumor promoter 12-O-tetradecanoyl-phorbol 13-acetate (TPA) in HepG2." (PMID 34571852, 2021). "Consistently, the clinical correlation between the expression of EZH2, KLF-6, Sp-1, and SNHG6 in patient tumor samples also showed that both EZH2 and Sp-1 displayed the positive correlation with SNHG6, whereas KLF6 and p21 exhibited the negative correlation with SNHG6." (PMID 33431838, 2021). "The ARNT/Sp1/c-Jun complex also regulates MDR1 expression and EGF-induced gene expression, such as that of cyclooxygenase-2, p21WAF1/CIP1 and 12(S)-lipoxygenase, which contribute to cancer drug resistance and tumor metastasis." (PMID 33446631, 2021). "SP1 was overexpressed in AML samples, and exerted pro-tumor activity in leukemia." (PMID 34006845, 2021). "Furthermore, a study reported that specificity protein 1 (SP1)-mediated upregulation of the lncRNA LINC00152 in GBC in vitro and in vivo induced proliferation and tumor growth via the PI3K/AKT pathway." (PMID 34944491, 2021). "In this study, we found that SP1 is highly expressed in ESCC, and accelerates tumor metastasis." (PMID 31892989, 2020). "Other candidate markers with significantly altered mRNA levels from the qPCR array (SP1, E2F1, TCF7L2) exhibited comparable levels between tumor and adjacent normal tissues using immunohistochemistry without evident heterogeneity in terms of spatial distribution (data not shown)." (PMID 33063251, 2020). "In this study, we revealed that ZLM-7 could inhibit tumor growth and angiogenesis of BC, which largely depended on inhibitory of VEGFA expression via suppressing miR-212-3p/Sp1 signal axis." (PMID 33187481, 2020). "There was a negative correlation between SP1 mRNA and hsa-miR-149-5p in tumor and adjacent normal tissues (r = −0.81, −0.77)." (PMID 31270251, 2019).